FAHD1 (FAH domain containing oxaloacetate decarboxylase 1)
Description:
Tautomerase that converts enol-oxaloacetate, a strong inhibitor of succinate dehydrogenase, to the physiological keto form of oxaloacetate. It is thereby required to maximize aerobic respiration efficiency by preventing succinate dehydrogenase inhibition. Also acts as a weak oxaloacetate decarboxylase (ODx), catalyzing the decarboxylation of oxaloacetate (OAA) to pyruvate and CO(2), and as such is likely a regulatory enzyme in the TCA cycle. Also displays acylpyruvase activity, being able to hydrolyze acetylpyruvate and fumarylpyruvate in vitro. Exhibits only a weak hydrolase activity on methylacetopyruvate and acetylacetone, and no activity toward acetoacetyl-CoA.
Synonyms: ODx; C16orf36; YISKL; DKFZP566J2046
Tractability: Small molecule: it has a binding pocket of medium quality. PROTAC: its protein half-life has been measured.
Target class: Enzyme; Hydrolase
Gene: Protein-coding gene on chromosome 16 (1,826,967 to 1,840,207, forward strand). Ensembl gene ENSG00000180185.
Subcellular location: Mitochondrion; Cytoplasm, cytosol
Subcellular location (Human Protein Atlas): Mitochondria; Nucleoplasm
Pathways (Reactome):
Metabolism: Pyruvate metabolism
Gene Ontology:
Molecular function: acetylpyruvate hydrolase activity; acylpyruvate hydrolase activity; fumarylpyruvate hydrolase activity; oxaloacetate decarboxylase activity; oxaloacetate tautomerase activity; catalytic activity
Biological process: oxaloacetate metabolic process
Cellular component: cytosol; mitochondrion; nucleoplasm; mitochondrial matrix
Genetic constraint (gnomAD): Loss-of-function variants: 15 observed, 14.9 expected, observed/expected ratio (o/e) 1.01, 90% interval 0.67 to 1.54. The upper end of that interval is the gene's LOEUF score, 1.54, which puts it in group 6 of 6, group 1 being the genes least tolerant of losing a copy. Missense variants: 351 observed, 316.14 expected, observed/expected ratio (o/e) 1.11, 90% interval 1.02 to 1.21. Synonymous variants: 153 observed, 136.86 expected, observed/expected ratio (o/e) 1.12, 90% interval 0.98 to 1.28.
Homologues: Orthologues: chimpanzee FAHD1 (95% identical), macaque FAHD1 (95% identical), pig FAHD1 (91% identical), dog FAHD1 (88% identical), rat Fahd1 (88% identical), mouse Fahd1 (88% identical), zebrafish fahd1 (66% identical), tropical clawed frog fahd1 (66% identical), Caenorhabditis elegans fahd-1 (45% identical). Paralogues in human: FAHD2A (37% identical), FAHD2B (36% identical), FAH (29% identical).
Diseases named in the same sentence as FAHD1 in open-access papers:
FAHD1 is named in the same sentence as 12 diseases in open-access papers, as found by Europe PMC text mining. Sharing a sentence is not in itself a finding about the gene and the disease. The quoted sentences say what the papers report.
breast carcinoma (5 papers, 2019 to 2025). "FAHD1 has been identified as a potential target for breast cancer cells reliant on glutamine metabolism." (PMID 39642098, 2025). "FAHD1 knockdown in breast cancer cells not only reduces complex II activity, likely due to oxaloacetate accumulation, but also has broader metabolic consequences." (PMID 39642098, 2025). "These metabolic shifts vary depending on the availability of substrates like glucose and glutamine, highlighting the importance of FAHD1 in maintaining metabolic flexibility in breast cancer cells." (PMID 39642098, 2025). "Depleting FAHD1 through siRNA‐mediated knockdown significantly hindered the proliferation of basal breast cancer cell lines, such as BT‐20, and reduced the growth of luminal cell line MCF‐7 when cultured with glutamine as the primary carbon source." (PMID 39642098, 2025). "Depletion of the mitochondrial enzyme FAHD1 in breast cancer cells leads to metabolic stress and cell death in triple‐negative BT‐20 cells." (PMID 35962472, 2022). "Based on these findings, we investigated the expression of FAHD1 in a selection of both luminal and basal breast cancer cell lines, including MCF‐7, T47D, BT‐20 and MDA‐MB‐231." (PMID 35962472, 2022). "The mitochondrial enzyme fumarylacetoacetate hydrolase domain‐containing protein 1 (FAHD1) was identified to be upregulated in breast cancer tissues." (PMID 35962472, 2022). "In this study, we described the role of the mitochondrial oxaloacetate decarboxylase FAHD1 in breast cancer." (PMID 35962472, 2022). "Immuno‐histochemical staining revealed elevated levels of FAHD1 in 75% of cells in malignant tissue derived from human breast cancer patients." (PMID 35962472, 2022). "Here, we show that FAHD1 is indispensable for the survival of BT‐20 cells, representing the basal breast cancer cell type." (PMID 35962472, 2022). "This study aims to further characterize the metabolic function of FAHD1 in breast cancer and to contribute new insights into the regulatory network that depends on its ODx activity in the TCA cycle." (PMID 35962472, 2022). "A lentiviral knock‐down of FAHD1 in the breast cancer cell lines MCF‐7 and BT‐20 results in lower succinate dehydrogenase (complex II) activity." (PMID 35962472, 2022). "To address a potential role of FAHD1 in the metabolic wiring of human breast cancer cells, we aimed to generate FAHD1 KD models in luminal MCF‐7 and basal BT‐20 cells." (PMID 35962472, 2022). "Moreover, FAHD1's involvement in glutamine metabolism and its impact on cancer cell proliferation, particularly in aggressive breast cancer subtypes, underscores its potential as a therapeutic target." (PMID 39642098, 2025). "Similar findings were observed when examining the impact of FAHD1 depletion in breast cancer cells." (PMID 38649439, 2024). "One key finding reported in the present study is the unexpected decrease of GLS protein levels in FAHD1‐depleted breast cancer cells, which may have widespread consequences for the metabolic state of these cells." (PMID 35962472, 2022).
osteosarcoma (1 paper, 2024). A usually aggressive malignant bone-forming mesenchymal neoplasm, predominantly affecting adolescents and young adults. "The impact of overexpressing the mitochondrial enzyme FAHD1 in the osteosarcoma cell model U2OS was investigated, resulting in reduced ROS levels." (PMID 38649439, 2024). "This study investigated the impact of overexpressing the mitochondrial enzyme Fumarylacetoacetate hydrolase domain-containing protein 1 (FAHD1) in human osteosarcoma epithelial cells (U2OS) in vitro." (PMID 38649439, 2024). "The findings elucidate that FAHD1 regulates the PEP-PYR-OAA node, a pathway identified as highly relevant for osteosarcoma cell progression." (PMID 38649439, 2024).
Rb (1 paper, 2022). "Strikingly, we also identified the mitochondrial TCA-related FAHD1 gene (p < 0.05, FC = 2.38) to be significantly upregulated in Rb subjects." (PMID 35626705, 2022).
cancer (5 papers, 2021 to 2025). A tumor composed of atypical neoplastic, often pleomorphic cells that invade other tissues. "FAHD1 has been implicated in regulating complex II activity in cancer cells, underscoring its broader impact in cellular metabolism and disease states." (PMID 39642098, 2025). "FAHD1+epi cells interact with cancer-associated fibroblasts through ITGB2-mediated interactions, facilitating the formation of a transforming growth factor-β/vascular endothelial growth factor-enriched niche that promotes immune evasion." (PMID 40814172, 2025). "Of significant interest, a surprising correlation was noted between the expression of the T192S variant of FAHD1 in certain animals exhibiting long lifespans and resistance to cancer." (PMID 38649439, 2024). "Additionally, the study demonstrates that the catalytically enhanced FAHD1 variant T192S, observed in species with longevity and increased cancer resistance, may shift cellular metabolism from glycolysis towards glutaminolysis." (PMID 38649439, 2024). "After more than 12 years of research, it is increasingly clear that FAHD1's contributions to cellular metabolism, oxidative stress regulation, and disease processes such as cancer and aging warrant recognition in both textbooks and comprehensive reviews." (PMID 39642098, 2025). "Understanding FAHD1's multifaceted roles in these metabolic pathways can provide insights into its potential implications for conditions like cancer and metabolic diseases." (PMID 39642098, 2025). "Members of the FAH superfamily, such as FAHD1, are involved in mitochondrial metabolism, and their dysregulation might affect both metabolic and apoptotic pathways in cancer cells." (PMID 39642098, 2025). "Notably, ITGB2 has been implicated in cancer-associated fibroblast (CAF)-mediated glycolytic activation and pyruvate-lactate secretion, suggesting a feedforward loop where FAHD1+epi cells engage CAFs through ITGB2 to reinforce metabolic symbiosis." (PMID 40814172, 2025). "If these hypotheses are confirmed, FAHD1 could become a pivotal target for therapeutic interventions in cancer, metabolic disorders, and immune‐related diseases." (PMID 39642098, 2025). "In breast and prostate cancers, FAHD1 inhibition might alter metabolic pathways critical for cancer cell survival, making it a potential target for cancer therapy." (PMID 39642098, 2025). "The review delves into the broader implications of FAHD1 in mitochondrial function, emphasizing its roles in mitigating reactive oxygen species (ROS) levels and regulating complex II activity, particularly in cancer cells." (PMID 39642098, 2025). "This regulatory mechanism differs from the conventional pyruvate dehydrogenase (PDH)-PDK axis, suggesting that FAHD1, as a crucial regulator of tumor metabolic reprogramming, may serve as a potential target for cancer therapy and metabolic interventions." (PMID 40814172, 2025). "Understanding the possible regulation of KGA and GAC isoforms by FAHD1 regulation may help to identify potential therapeutic targets for cancer treatment." (PMID 38649439, 2024). "In addition to these, we also identified some novel genes among the 14-CpG markers that were not previously associated with cancer recurrences such as IFFO1, ALKAL1, FAHD1, FSTL4, SLC7A9, IQCJ-SCHIP1, CLDN11 and three other CpGs at intergenic regions." (PMID 34207933, 2021).
infection (4 papers, 2012 to 2022). The state of being infected such as from the introduction of a foreign agent such as serum, vaccine, antigenic substance or organism. "To be able to collect information on the metabolic fate of FAHD1‐depleted BT‐20 cells, we decided to characterize metabolic consequences of FAHD1 KD in early passages (day 5 post‐infection) of freshly infected BT‐20 cells." (PMID 35962472, 2022). "Similar to the results obtained with MCF‐7, transient infection of BT‐20 cells with a lentiviral vector carrying a shRNA targeting FAHD1, reduced FAHD1 expression relative to control cells." (PMID 35962472, 2022). "Protein lysates were obtained from cells on day 5 post‐infection, when cell numbers were still equivalent between FAHD1 KD cells and controls, and analysed for levels of FAHD1 and GLS." (PMID 35962472, 2022). "Starting from day 3 (D3) post infection, we observed a dramatic increase in the formation of colonies in Fahd1-KO-infected MEFs as compared to WT based on the number of GFP-positive colonies." (PMID 34440809, 2021). "At D1 post infection, the percentage of infected MEFs, as indicated by the GFP fluorescence, was similar between WT and Fahd1-KO MEFs." (PMID 34440809, 2021).
tumor (2 papers, 2024 to 2025). "Analysis of 30 paired HCC tumor and adjacent normal tissues revealed significant upregulation of FAHD1 mRNA levels in tumors." (PMID 40814172, 2025). "Beyond its tumor-intrinsic effects, we observed FAHD1+epi cells actively reshaping the TME through ITGB2-dependent crosstalk with CAFs." (PMID 40814172, 2025). "FAHD1 overexpression correlates with poor prognosis and shapes the immunosuppressive tumor microenvironment, revealing its potential as a therapeutic target to improve HCC outcomes." (PMID 40814172, 2025). "By identifying FAHD1 as a linchpin connecting mitochondrial reprogramming, stromal co-option, and immune evasion, we provide a roadmap for targeting metabolic plasticity to disrupt tumor ecosystems." (PMID 40814172, 2025). "Future efforts to therapeutically exploit this axis may benefit from dual-pronged strategies that simultaneously cripple tumor-intrinsic metabolism (e.g., FAHD1 inhibition) and remodel the immunosuppressive niche, potentially overcoming limitations observed with earlier metabolic agents like DCA." (PMID 40814172, 2025). "The results showed that tumor regions in HCC-1L and HCC-3L showed predominant localization of FAHD1+epi." (PMID 40814172, 2025). "Collectively, these findings establish FAHD1 as a key driver of HCC progression, promoting tumor cell proliferation, migration, and invasion." (PMID 40814172, 2025). "Through PC suppression-mediated restriction of OAA regeneration, FAHD1 constrains TCA cycle progression while destabilizing the phosphoenolpyruvate (PEP)-pyruvate-OAA metabolic axis, which is essential for maintaining metabolic plasticity in proliferating tumor cells." (PMID 40814172, 2025).
metabolic disorders (1 paper, 2025). "The intricate connections between FAHD1 and the urea cycle could have broader implications for metabolic diseases and immune regulation, suggesting a possible indirect regulation of the folate cycle (up to arachidonic acid pathways)." (PMID 39642098, 2025).
neurodegenerative disease (1 paper, 2025). A disorder of the central nervous system characterized by gradual and progressive loss of neural tissue and neurologic function. "FAHD1 is a critical regulator of neuronal ferroptosis and may serve as a potential therapeutic target for the treatment of neurodegenerative diseases and CNS injuries." (PMID 41041519, 2025).
neurological diseases (1 paper, 2025). "In conclusion, this study demonstrates that FAHD1 plays a central role in the pathogenesis of neuronal ferroptosis and suggests that FAHD1 may represent a potential therapeutic target for neurological diseases." (PMID 41041519, 2025).
FAHD1 also shares sentences with these, for which no sentence is quoted: hepatocellular carcinoma (1 paper); periodontitis (1); testis cancer (1).